CNOT6 (CCR4-NOT transcription complex subunit 6)
Description:
Poly(A) nuclease with 3'-5' RNase activity. Catalytic component of the CCR4-NOT complex which is one of the major cellular mRNA deadenylases and is linked to various cellular processes including bulk mRNA degradation, miRNA-mediated repression, translational repression during translational initiation and general transcription regulation. Additional complex functions may be a consequence of its influence on mRNA expression. Involved in mRNA decay mediated by the major-protein-coding determinant of instability (mCRD) of the FOS gene in the cytoplasm. In the presence of ZNF335, enhances ligand-dependent transcriptional activity of nuclear hormone receptors, including RARA. The increase of ligand-dependent ESR1-mediated transcription is much smaller, if any. Mediates cell proliferation and cell survival and prevents cellular senescence.
Synonyms: CCR4; CCR4a; KIAA1194
Tractability: PROTAC: ubiquitination databases record sites on it; its protein half-life has been measured.
Target class: Enzyme; Hydrolase
Gene: Protein-coding gene on chromosome 5 (180,494,334 to 180,578,401, forward strand). Ensembl gene ENSG00000113300.
Subcellular location: Cytoplasm; Nucleus
Subcellular location (Human Protein Atlas): Cytosol
Pathways (Reactome):
Developmental Biology: Activation of anterior HOX genes in hindbrain development during early embryogenesis; M-decay: degradation of maternal mRNAs by maternally stored factors
Metabolism of RNA: Deadenylation of mRNA
Gene Ontology:
Molecular function: poly(A)-specific ribonuclease activity; protein binding; RNA exonuclease activity; transcription coactivator activity; 3'-5'-RNA exonuclease activity; catalytic activity
Biological process: miRNA-mediated gene silencing by mRNA destabilization; nuclear-transcribed mRNA catabolic process, no-go decay; nuclear-transcribed mRNA poly(A) tail shortening; positive regulation of cell population proliferation; positive regulation of cytoplasmic mRNA processing body assembly; positive regulation of DNA-templated transcription
Cellular component: CCR4-NOT complex; membrane; cytoplasm; cytosol; nucleus
Genetic constraint (gnomAD): Loss-of-function variants: 10 observed, 52.99 expected, observed/expected ratio (o/e) 0.19, 90% interval 0.12 to 0.32. The upper end of that interval is the gene's LOEUF score, 0.32, which puts it in group 1 of 6, group 1 being the genes least tolerant of losing a copy. Missense variants: 396 observed, 671.46 expected, observed/expected ratio (o/e) 0.59, 90% interval 0.54 to 0.64. Synonymous variants: 222 observed, 248.41 expected, observed/expected ratio (o/e) 0.89, 90% interval 0.8 to 1.
Homologues: Orthologues: chimpanzee CNOT6 (100% identical), macaque CNOT6 (99% identical), dog CNOT6 (98% identical), pig CNOT6 (97% identical), rabbit CNOT6 (97% identical), mouse Cnot6 (96% identical), rat Cnot6 (96% identical), guinea pig CNOT6 (92% identical), zebrafish cnot6a (86% identical), zebrafish cnot6b (84% identical), Drosophila melanogaster twin (56% identical), Caenorhabditis elegans ccr-4 (39% identical), and 2 more. Paralogues in human: CNOT6L (79% identical), PDE12 (22% identical), ANGEL2 (19% identical), NOCT (18% identical), ANGEL1 (18% identical).
Diseases named in the same sentence as CNOT6 in open-access papers:
CNOT6 is named in the same sentence as 21 diseases in open-access papers, as found by Europe PMC text mining. Sharing a sentence is not in itself a finding about the gene and the disease. The quoted sentences say what the papers report.
lung carcinoma (5 papers, 2015 to 2022). "The altered expression of CNOT6 or CNOT6L has been detected in acute leukemia and androgen-independent prostate cancer cells, and single-nucleotide polymorphisms (SNPs) in CNOT6 have been associated with pediatric acute lymphoblastic leukemia and lung cancer." (PMID 35159331, 2022). "CNOT6 encodes Ccr4a protein that was a deadenylase subunit of the CCR4-Not complex, and the CNOT6 rs2453176 C>T polymorphism was related to an increased risk of lung cancer." (PMID 33251144, 2020). "Regarding CNOT6, only one out of the 11 patients (<10 %) who had a distant metastasis was overexpressing CNOT6, an observation that could imply a possible protective role of this enzyme over lung cancer invasion and can be a strong indicator of non-metastasis in SCC (p = 0.007)." (PMID 26541675, 2015).
acute leukemia (2 papers, 2020 to 2022). A clonal (malignant) hematopoietic disorder with an acute onset, affecting the bone marrow and the peripheral blood. "Moreover, the CNOT6 expression level was significantly lower in acute leukemia patients than healthy controls." (PMID 33251144, 2020).
acute lymphoblastic leukemia (2 papers, 2014 to 2022). Leukemia with an acute onset, characterized by the presence of lymphoblasts in the bone marrow and the peripheral blood. "It is also worth noting that some tumors demonstrate decreased expression of CNOT6, while a higher expression of CNOT6 has been reported in acute lymphoblastic leukemia (ALL), acute myeloid leukemia (AML) and androgen-independent prostate cancer." (PMID 35159331, 2022). "CNOT6 is overexpressed in acute lymphoblastic leukemia (ALL), acute myeloid leukemia (AML) and androgen-independent prostate cancer cells, which suggests that an altered expression of CNOT6 may play a role in tumorigenesis." (PMID 35159331, 2022).
acute myeloid leukemia (2 papers, 2014 to 2022). Acute myeloid leukemia (AML) is a group of neoplasms arising from precursor cells committed to the myeloid cell-line differentiation. "The expression of CNOT6L and CNOT7 was reportedly down-regulated in samples of leukemia cells taken from ALL and AML (acute myeloid leukemia) patients compared to normal blood cells, while the expression of CNOT6 was slightly up-regulated." (PMID 25191340, 2014).
breast carcinoma (2 papers, 2015 to 2022). "The knockdown of CNOT6 and/or CNOT6L reduced cell proliferation and cell survival, while gene expression profiling reveals that the enzymes regulate distinct gene sets associated with breast cancer cell proliferation, apoptosis, and the inhibition of tumor development." (PMID 35630580, 2022). "To extend the previous analysis, we included data from silencing of CNOT6, CNOT6L, CNOT7, and CNOT8 from another cell line, namely, MCF7 (derived from pleural effusion of breast carcinoma), based on previous studies." (PMID 35630580, 2022).
female infertility (2 papers, 2025). Diminished or absent ability of a female to achieve conception. "Cnot6/6l whole-body deletion results in female infertility due to defective maternal mRNA degradation during oocyte maturation." (PMID 40814964, 2025).
Dengue virus infection (1 paper, 2022). "Furthermore, CNOT2 supports Dengue virus infection by inhibiting JAK-STAT antiviral signaling via its interaction with CNOT6/6L and CNOT7/8 deadenylases." (PMID 36140672, 2022).
HCMV infection (1 paper, 2023). "To establish whether CCR4‐NOT complex components are altered in their abundance during HCMV infection, we monitored expression of nucleases CNOT6, 6L, 7, and 8 and nonenzymatic modules CNOT1, 2 3, by immunoblot where reliable antibodies could be sourced and RT‐qPCR where not." (PMID 37846490, 2023).
lung squamous cell carcinoma (1 paper, 2020). "Previous research found that CNOT6 was overexpressed in non-metastatic lung squamous cell carcinoma, and it may be associated with low invasiveness." (PMID 33251144, 2020).
metastatic tumors (1 paper, 2015). "PARN overexpression correlated with younger patient age and CNOT6 overexpression with non-metastatic tumors." (PMID 26541675, 2015). "Further, PARN or NOC overexpression is observed in samples from patients with increased overall survival, while in samples derived from non-metastatic tumors the expression of CNOT6 was increased." (PMID 26541675, 2015). "We therefore examined the expression of these deadenylases using comparative quantification between SCC specimens and their matched non-pathological tissues, and we observed that PARN and CNOT6 overexpression correlated with younger patient age and non-metastatic tumors, respectively." (PMID 26541675, 2015).
pontocerebellar hypoplasia (1 paper, 2022). Pontocerebellar hypoplasias (PCH) are a rare heterogeneous group of diseases characterized by hypoplasia and atrophy and/or early neurodegeneration of the cerebellum and pons. "EXOSC9 is linked to the rare disorder pontocerebellar hypoplasia, the expression of CNOT6 is reported to be altered in several types of tumor cells, and it has been suggested that it plays a role in preventing cell death and senescence." (PMID 35159331, 2022).
sensitization (1 paper, 2014). "SNPs in or near JAK2, CNOT6, MAML1, CD40, IL-4R, and IL-5RA genes were associated with allergic sensitization and SNPs in or near JAK1, JAK3, IL5RA, FCER1A, and ADAM33 genes were associated with cockroach sensitization." (PMID 25505553, 2014).
cancer (7 papers, 2013 to 2024). A tumor composed of atypical neoplastic, often pleomorphic cells that invade other tissues. "Some of these reported targets are cancer-related and are associated with carcinogenesis (such as SPRY2, SKY and SRSF3), cancer prognosis (such as CNOT6, RECK and GID4) or cancer cell plasticity (such as RMND5A)." (PMID 33804639, 2021). "Our results revealed further cancer-relevant target genes including STAG2, CNOT6, SOX2, CDC25A and SFRS3." (PMID 23358700, 2013). "The depletion of CNOT6L in cancer MCF7 cells and mouse NIH3T3 cells impairs cell proliferation, but highlights differences in the expression of specific genes assuming cell type-specific roles for the CNOT6 and CNOT6L." (PMID 35630580, 2022). "Regarding the levels of deadenylases in cancer, it is shown that in acute types of leukemia (AML, ALL), the levels of both PARN and CNOT6 increase compared to non-malignant clinical samples, while the opposite is the case for CNOT6L and CNOT7." (PMID 35630580, 2022).
tumor (4 papers, 2016 to 2022). "Further investigations of the RNA binding proteins that recruit transcripts for deadenylation and studies into possible roles of the other CCR4-NOT deadenylase subunits Cnot6 and Cnot6l in metastatic progression may reveal additional important insights into tumor autonomous metastatic mechanisms." (PMID 26807845, 2016).
infection (1 paper, 2015). The state of being infected such as from the introduction of a foreign agent such as serum, vaccine, antigenic substance or organism. "D39 interaction up-regulated expression in PMC for the gene encoding the diazepam binding inhibitor protein, which has a role in increasing host cell numbers and increased expression of the CNOT6 and ATF4 genes has been reported to be important for protecting cells from infection stress and death." (PMID 26566142, 2015).
CNOT6 also shares sentences with these, for which no sentence is quoted: infertile (1 paper); male infertility (1); Pleural effusion (1); prostate carcinoma (1); rectum cancer (1); stomach adenocarcinoma (1).